OR2T6 (olfactory receptor family 2 subfamily T member 6)
Description:
Odorant receptor.
Synonyms: OR2T6P; OR2T9; OST703
Tractability: Antibody: UniProt places it where antibodies can reach, with medium confidence; UniProt predicts a signal peptide or a membrane-spanning region; its Gene Ontology location is reachable by antibodies, with medium confidence.
Gene: Protein-coding gene on chromosome 1 (248,375,746 to 248,391,811, forward strand). Ensembl gene ENSG00000198104.
Subcellular location: Cell membrane
Pathways (Reactome):
Sensory Perception: Expression and translocation of olfactory receptors
Gene Ontology:
Molecular function: olfactory receptor activity; G protein-coupled receptor activity
Biological process: detection of chemical stimulus involved in sensory perception of smell; G protein-coupled receptor signaling pathway
Cellular component: plasma membrane; membrane
Genetic constraint (gnomAD): Loss-of-function variants: 1 observed, 0.17 expected, observed/expected ratio (o/e) 5.78. That is too few expected variants to judge how well the gene tolerates losing a copy. Missense variants: 420 observed, 403.95 expected, observed/expected ratio (o/e) 1.04, 90% interval 0.96 to 1.13. Synonymous variants: 174 observed, 154.16 expected, observed/expected ratio (o/e) 1.13, 90% interval 1 to 1.28.
Homologues: Orthologues: chimpanzee OR2T6 (98% identical), macaque OR2T6 (94% identical), pig OR2T6 (84% identical), dog OR2T6 (82% identical), mouse Or2t6 (81% identical), rat Or2t6 (81% identical), guinea pig OR2T6 (75% identical). Paralogues in human: OR2T1 (73% identical), OR2T27 (65% identical), OR2T2 (63% identical), OR2T35 (63% identical), OR2T11 (63% identical), OR2T29 (59% identical), OR2T5 (59% identical), OR2T4 (58% identical), OR2T10 (54% identical), OR2V2 (52% identical), OR2T12 (52% identical), OR2T33 (51% identical), and 80 more.
Diseases named in the same sentence as OR2T6 in open-access papers:
OR2T6 is named in the same sentence as 7 diseases in open-access papers, as found by Europe PMC text mining. Sharing a sentence is not in itself a finding about the gene and the disease. The quoted sentences say what the papers report.
breast carcinoma (4 papers, 2019 to 2023). "OR2T6 is overexpressed in breast cancer tissues, whereas OR51E2 is overexpressed in prostate cancer and enhances tumor cell invasiveness via PTEN loss." (PMID 36779496, 2023). "Results showed that the transcriptional levels of OR2T6 were significantly higher in breast cancer tissues than in normal ones (p < 0.05)." (PMID 31781505, 2019). "We first examined the mRNA levels of OR2T6 in normal breast tissues (n = 9 samples) and breast cancer tissues (n = 41 samples) by real-time quantitative PCR." (PMID 31781505, 2019). "In our research, we showed that alteration of OR2T6 expression significantly changed the protein levels of the epithelial and mesenchymal markers in breast cancer cells." (PMID 31781505, 2019). "To explore the role of OR2T6 in the proliferation and apoptosis of breast cancer cells, we performed EdU staining and flow cytometry assays in MCF-7 and MDA-MB-231 cells." (PMID 31781505, 2019). "In our present study, 28 of 102 cases of breast cancer showed cytoplasmic OR2T6 localization, while one case exhibited membranous localization." (PMID 31781505, 2019). "OR2T6 expression in breast cancer tissues was significantly higher than that in normal breast tissues, and its expression was tightly associated with tumor staging and lymph node metastasis." (PMID 31781505, 2019). "Here we first revealed that the olfactory receptor family 2, subfamily T, member 6 (OR2T6) was significantly over-expressed in breast cancer tissues compared with normal breast tissues." (PMID 31781505, 2019). "Here, we demonstrated that OR2T6 enhanced the proliferation, invasion, and migration of breast cancer cells and inhibited apoptosis of these cells." (PMID 31781505, 2019). "The data indicated that OR2T6 inhibited apoptosis, thereby facilitating the transformation of breast cancer cells." (PMID 31781505, 2019). "We next investigated the correlation of OR2T6 expression with the clinicopathological characteristics of breast cancer patients." (PMID 31781505, 2019). "OR2T6, which is overexpressed in breast cancer cell lines (MCF-7 and MDA-MB-231), was associated with the progression of breast cancer cells via the epithelial–mesenchymal transition (EMT)-mediated mitogen-activated protein kinase (MAPK) pathway and suppression of apoptosis." (PMID 34065710, 2021). "Thus, we concluded that OR2T6, as a novel oncogene, contributed to the progression of breast carcinoma by the initiation of EMT and MAPK/ERK pathway." (PMID 31781505, 2019). "In the present study, we identified that OR2T6, as a new oncogene, might be involved in the initiation and progression of breast cancer." (PMID 31781505, 2019). "In the present study, our findings in OR2T6 may help to broaden the molecular mechanism of GPCRs-induced breast cancer and to develop new therapeutic strategies for breast cancer patients in the future." (PMID 31781505, 2019). "Furthermore, when we transfected breast cancer cells with siRNA specific to OR2T6, migration, and invasion were dramatically reduced in MCF-7 cells (p = 0.006 and 0.005, respectively) and MDA-MB-231 cells (p = 0.017 and p < 0.01, respectively)." (PMID 31781505, 2019). "Moreover, cBioPortal analysis confirmed the genetic alterations of OR2T6 gene in large-scale of breast cancer." (PMID 31781505, 2019). "We next investigated the molecular signaling pathways via which OR2T6 functions in breast cancer." (PMID 31781505, 2019). "Up-regulation of OR2T6 expression in breast cancer may enhance migration and invasion by initiating the EMT, and promote proliferation and inhibit apoptosis via activation of the MAPK/ERK pathway." (PMID 31781505, 2019). "Thus, we speculated that OR2T6 was a novel cancer-related OR, and it might play a role in the maintenance of the malignant phenotype of breast cancer." (PMID 31781505, 2019). "Thus, OR2T6 might promote proliferation and inhibit the apoptosis of breast cancer cells via the initiation of the MAPK/ERK pathway." (PMID 31781505, 2019).
breast carcinoma (continued). "Thus, OR2T6 enhanced the proliferation of breast cancer cells." (PMID 31781505, 2019). "Human breast cancer tissues and cell lines highly express ORs, among which only three, OR2W3, OR2B6, and OR2T6, have established functions." (PMID 34065710, 2021). "Thus, OR2T6 plays an essential role in the promotion of the EMT process, and it might promote the migration and invasion of breast cancer cells via the initiation of EMT progression." (PMID 31781505, 2019).
hyperlipidemia (1 paper, 2022). "In addition, significant upregulation was observed in DPPA5, DNM3OS, OR2T6, OR8H1 in four complications including neuropathy, ketoacidosis, hyperlipidemia and PCOs (p < 0.01) (Boxplots 8C, 8D, 8F,8H, respectively)." (PMID 36175575, 2022).
lymph node metastasis (1 paper, 2019). "Statistical analysis showed that the positive expression of OR2T6 was tightly associated with lymph node metastasis (p = 0.002) and higher TNM (Tumor/Node/Metastasis) staging (p = 0.033), but not with patients' age, tumor size, or histological grade." (PMID 31781505, 2019).
cancer (1 paper, 2019). A tumor composed of atypical neoplastic, often pleomorphic cells that invade other tissues. "Consistent with this, the interference of OR2T6 notably decreased the percentage of proliferating cancer cells (p = 0.006)." (PMID 31781505, 2019). "Considering the multifaceted functions of OR2T6, future approaches targeting OR2T6 might have promising potential in cancer treatment." (PMID 31781505, 2019). "We identified that the olfactory receptor family 2, subfamily T, member 6 (OR2T6) was significantly higher in cancers with metastasis than in those without metastasis." (PMID 31781505, 2019).
OR2T6 also shares sentences with these, for which no sentence is quoted: tumor (2 papers); neuropathy (1); prostate carcinoma (1).